SPINK1 (serine peptidase inhibitor Kazal type 1)
Diseases named in the same sentence as SPINK1 in open-access papers (continued):
Sharing a sentence is not in itself a finding about the gene and the disease.
pancreatitis (continued). "To date, several pancreatitis-associated genes have been identified such as the cationic trypsinogen (PRSS1) gene and the serine protease inhibitor, Kazal type 1 (SPINK1) gene have been identified." (PMID 25157235, 2014). "Recently, functional analysis of pancreatitis-associated missense mutations was performed in the pancreatic secretory trypsin inhibitor (SPINK1) gene, which encodes pancreatic secretory trypsin inhibitor (PSTI)." (PMID 22577471, 2012). "Mutation in another gene, that codes the serine protease inhibitor Kazal type 1 (SPINK 1), has been found to act complementary to other genetic or environmental factors causing pancreatitis." (PMID 22934106, 2012). "Mutations in other genes such as anionic trypsinogen (PRSS2), the serine protease inhibitor Kazal type 1 (SPINK1), CFTR, chymotrypsinogen C (CTRC) and calcium-sensing receptor (CASR) are also associated with an increased risk for pancreatitis." (PMID 22133269, 2011). "However, recent studies demonstrated that prolonged cerulein hyperstimulation in Spink1-KOhet mice led to hallmarks of acute pancreatitis, underscoring SPINK1’s protective role in trypsin-dependent pancreatitis." (PMID 40427173, 2025). "This identified a heterozygous mutation (c.194 + 2 T > C) in the SPINK1 gene despite no familial history of pancreatitis reported by the parents." (PMID 40007874, 2025). "As controls, Japanese patients with alcohol-unrelated pancreatitis carrying pathogenic variants in PRSS1 or SPINK1, as well as those without pathogenic variants in pancreatitis susceptibility genes, were enrolled." (PMID 41247519, 2025). "To resolve this contradiction, we used CRISPR/Cas9-mediated genome editing to generate heterozygous Spink1-deleted mice (Spink1-KOhet) in the C57BL/6N strain and studied the effect of this allele in trypsin-independent and trypsin-dependent pancreatitis models." (PMID 38768901, 2024). "It is noteworthy that reduced SPINK1 levels modify disease severity without causing spontaneous pancreatitis." (PMID 38768901, 2024). "Moreover, tobacco smoke can alter gene expression, thus affecting the ratio of trypsinogen and serine protease inhibitor Kazal type 1 (SPINK1), which increases susceptibility to pancreatitis." (PMID 38877637, 2024). "Pancreatitis may occur when intrapancreatic trypsin activity overwhelms SPINK1 reserves, and trypsinogen autoactivation can proceed unimpeded." (PMID 38768901, 2024). "We investigated the prevalence of the SPINK1(N34S) mutation in patients with AAP compared to heavy alcohol users who had never suffered an episode of pancreatitis." (PMID 36555366, 2022). "Since the etiology of AP was exclusively alcohol-induced in our study, it is probable that some patients after the initial attack of pancreatitis develop recurrent attacks later if abstinence is not achieved, especially if they have SPINK1 mutation." (PMID 36555366, 2022). "In a comparison between AAP patients and alcoholics without pancreatitis, we demonstrate that the role of SPINK1 mutation is overrepresented as an individual risk factor for AAP." (PMID 36555366, 2022). "In the 2019 clinical diagnostic criteria for CP, mutations in established pancreatitis-associated genes, such as PRSS1 and SPINK1, are included in the diagnostic items for early stage CP, and the role of genetic testing in daily clinical practice is increasing." (PMID 35994093, 2022). "CaSR also inhibits cell proliferation in pancreatic cancer, and CaSR mutations, with or without SPINK1, cause pancreatitis." (PMID 36275616, 2022). "Our report suggests that in AAP patients SPINK1 mutations are prevalent in almost 9% of cases, which is significantly more than in healthy controls or alcoholics without pancreatitis." (PMID 36555366, 2022). "The prevalence of SPINK1 mutation was significantly lower in healthy controls (3.4%, n = 65: OR 2.72; 1.32–5.64) and very low in alcoholics without pancreatitis (1.0%, n = 1: 9.29; 1.15–74.74)." (PMID 36555366, 2022).
pancreatitis (continued). "The findings reported by the INSPPIRE were that at least one pancreatitis-related gene mutation was found in 48 and 73% of ARP and CP patients, respectively, and SPINK1 and PRSS1 mutations were more closely related to CP, and children with ARP with pathogenic PRSS1 variants rapidly progress to CP." (PMID 35958176, 2022). "Therefore, the inactivation of irregularly produced intrapancreatic PRSS1 by SPINK1 or by an unidentified serine protease (Rinderknecht’s enzyme Y) has been proposed to protect against pancreatitis." (PMID 34436220, 2021). "In 2000, a mutation in the serine protease inhibitor gene (Kazal type 1: SPINK1) was reported to be related to sporadic pancreatitis of unknown etiology." (PMID 33375361, 2020). "In addition, SPINK1 was originally identified as a trypsin inhibitor and is strongly elevated in patients with pancreatitis, where the level of elevation correlates with the disease severity." (PMID 25667658, 2015). "The pancreatitis in this patient was not due to gallstones or alcohol abuse, and analysis of genes known to be associated with pancreatitis, such as SPINK1, CFTR, PRSS1 and CTRC, did not reveal any mutations." (PMID 26082470, 2015). "However, FHH1 probands with pancreatitis typically harbour heterozygous mutations of both the CASR and serine protease inhibitor, Kazal type 1 (SPINK1) genes." (PMID 26082470, 2015). "In addition to PRSS1, CFTR, and SPINK1, the CTRC and CASR genes are additional risk factors that appear to increase risk of pancreatitis in the context of one of three primary susceptibility factors." (PMID 23230421, 2012). "While Spink1-null mice (previously referred to as Spink3-null) did not survive beyond two weeks, heterozygous Spink1-deficient mice exhibited reduced SPINK1 expression without altered susceptibility to transient cerulein-induced pancreatitis." (PMID 40427173, 2025). "Consequently, increasing pancreatic anti-trypsin defenses with exogenously introduced SPINK1 may be a viable option for the treatment and/or prevention of pancreatitis." (PMID 40753100, 2025). "The SPINK1 mutation usually acts as a disease modifier rather than causing pancreatitis on its own." (PMID 39687810, 2024). "Notably, her mother, who also carries the SPINK1 c.194 + 2T>C heterozygous variant, has not exhibited noticeable symptoms of pancreatitis in the past." (PMID 39564382, 2024). "Pathogenic variants of the SPINK1 and PRSS1 genes have the maximum impact on the risk of CP development in patients from different countries, as the products of these genes are key participants in the trypsin-dependent pathogenetic pathway of the pancreatitis development." (PMID 37389024, 2023). "However, pancreatitis-associated genetic tests are currently not covered by national health insurance in Japan, and it is still unclear how abnormalities in SPINK1 should be handled in the diagnostic criteria for hereditary pancreatitis." (PMID 35994093, 2022). "Our aim was to study the prevalence of SPINK1 (N34S) mutation in relation to known risk factors for non-gallstone pancreatitis in patients with AAP compared to heavy alcohol users who had never suffered an episode of pancreatitis." (PMID 36555366, 2022). "Overall, compared to normal children, previous studies have demonstrated the association of SPINK1 and PRSS1 with ARP and CP; nonetheless, using children with ARP as a reference in this study, PRSS1 mutations were more closely associated with CP and pancreatitis progression than SPINK1 mutations." (PMID 35958176, 2022). "Genetic abnormalities, such as SPINK1, PRSS1, and CFTR gene mutations, are the main risk factors for symptomatic PD in children, and these genetic variants lead to the blockage of the pancreatic duct due to highly viscous pancreatic secretions, inducing pancreatitis in children with PD." (PMID 34796156, 2021).
pancreatitis (continued). "The aetiology of paediatric pancreatitis, which includes infections, systemic diseases, trauma, drug induction, biliary system diseases, anatomical abnormalities and genetic cause (CFTR, PRSS1, SPINK1, CTRC mutations), is significantly different from that of adults." (PMID 34178894, 2021). "In the following years, loss-of-function variants in the pancreatic secretory trypsin inhibitor (SPINK1), calcium-sensing receptor (CASR) and chymotrypsinogen C (CTRC) genes, firmly established the pivotal role of prematurely activated trypsin within the pancreas in the etiology of pancreatitis." (PMID 30134826, 2018). "In contrast, the affected FHH3 proband did not harbour a mutation of SPINK1 or other genes associated with pancreatitis, and this proband's marked hypercalcaemia may have been sufficient to disrupt pancreatic function." (PMID 26082470, 2015). "Therefore, the pathogenesis of pancreatitis may be more complex, and further studies will be required to elucidate the role of SPINK1 in the onset of pancreatitis." (PMID 24932227, 2014). "Serine protease inhibitor Kazal type 1 (SPINK1) binds to prematurely activated intracellular trypsin, playing a protective role against pancreatitis." (PMID 39599919, 2024). "Among patients with pancreatitis referred for genetic testing, monoallelic CFTR PVs were most frequently identified followed by monoallelic SPINK1." (PMID 39172977, 2024). "So far, several genes with potential application in the diagnosis of pancreatitis have been described, including PRSS1, CFTR, CTRC, and SPINK1." (PMID 39457082, 2024). "Four patients (4.1%), 3 (3.1%) with a SPINK1 c.194 + 2T>C variation and 1 (1.0%) with a PRSS1 p.Arg122His variation, experienced multiple recurrent pancreatitis episodes after surgical resection for chronic pancreatitis." (PMID 35171259, 2022). "Hence, due to the absence of any other risk factors for pancreatitis, based on his history, clinical presentation, absence of any variations in SPINK1 gene, and minimal pancreatic calcifications on imaging findings, he was diagnosed with ICP and treated symptomatically." (PMID 27957355, 2016). "SPINK1 N34S mutation is overexpressed in AAP patients compared to healthy controls and the prevalence was remarkably low in alcoholics without pancreatitis." (PMID 36555366, 2022). "The prevalence of the SPINK1 mutation is overrepresented in AAP patients and very low in alcoholics without pancreatitis." (PMID 36555366, 2022). "In addition, variations in the pancreatitis-related genes CFTR (8 cases [0.8%]) and SPINK1 (21 cases [2.1%]) were frequent in patients with PDAC." (PMID 35171259, 2022). "The patient did not have known pancreatitis-associated mutations, such as PRSS1, SPINK1, CTRC, CPA1, or TRPV6." (PMID 36419930, 2022). "Case 1: Eight months old female child suffering from constipation, recurrent vomiting and failure to thrive, family history of recurrent pancreatitis without mutations in the PRSS1 and SPINK1 genes." (PMID 33990208, 2021). "Because CFTR mutations are not necessarily correlated with the onset of pancreatitis, PRSS1, SPINK1 and CTRC mutations may also lead to pancreatitis." (PMID 36835437, 2023). "The SPINK1 mutants had a relatively more severe variety of pancreatitis as compared to non-mutants." (PMID 33996293, 2021). "CP might cluster in families, and in many of these affected subjects as well as young patients without a family history of pancreatitis, mutations in the genes coding for cationic trypsinogen (PRSS1), pancreatic secretory trypsin inhibitor (SPINK1) and chymotrypsinogen C (CTRC) can be identified." (PMID 24260417, 2013).
chronic pancreatitis (61 papers, 2006 to 2025). A chronic inflammatory process causing damage and fibrosis of the pancreatic parenchyma. "Inborn loss-of-function mutations in the SPINK1 gene increase risk for chronic pancreatitis in humans." (PMID 40753100, 2025). "The association of loss-of-function (LoF) SPINK1 variants with chronic pancreatitis (CP; OMIM #167800) supports this protective role." (PMID 41009946, 2025). "Taken together, the findings strongly support the notion that loss-of-function SPINK1 mutations in humans increase chronic pancreatitis risk in a trypsin-dependent manner." (PMID 38768901, 2024). "Genes, such as CFTR, PRSS1, and SPINK1, are involved in trypsinogen activation and regulation, with mutations contributing to recurrent acute episodes and progression to chronic pancreatitis." (PMID 39595191, 2024). "Heterozygous SPINK1 mutations are strong risk factors for chronic pancreatitis in humans, yet heterozygous disruption of mouse Spink1 yielded no pancreatic phenotype." (PMID 38768901, 2024). "Heterozygous Spink1 deficiency caused more severe acute pancreatitis after prolonged cerulein stimulation and promoted chronic pancreatitis after the cerulein-induced acute episode, and in two strains of trypsinogen mutant mice with spontaneous disease." (PMID 38768901, 2024). "SPINK1 is a protease inhibitor of trypsin in the pancreas, whose mutation usually relates to chronic pancreatitis." (PMID 38827297, 2024). "Trypsinogen mutant mice carrying the Spink1-KOhet allele exhibited strikingly more severe chronic pancreatitis than the respective parent strains." (PMID 38768901, 2024). "Loss-of-function variants in the SPINK1 gene increase susceptibility to chronic pancreatitis through the trypsin-dependent pathway." (PMID 38414044, 2024). "Specifically, the patient carrying the SPINK1 (c.194 + 2T>C) variant had a history of chronic pancreatitis." (PMID 37234870, 2023). "SPINK1 pathogenic variants act as a risk modifier in recurrent acute pancreatitis, thereby lowering the threshold for developing chronic pancreatitis induced by other genetic or environmental factors." (PMID 37603299, 2023). "Prior research has suggested a link between mutations in the gene SPINK1 and an increased likelihood of developing pancreatic cancer, particularly in individuals who suffered from chronic pancreatitis." (PMID 38093163, 2023). "SPINK1 mutations are a stronger risk factor in cases of chronic pancreatitis associated with recurrent trypsin activation." (PMID 36434531, 2022). "Loss-of-function genetic variants of SPINK1 increase the risk for chronic pancreatitis, often by diminishing inhibitor expression or secretion." (PMID 33515547, 2021). "Previous studies have claimed a correlation of SPINK1 mutations with a higher risk for pancreatic cancer, particularly in patients with chronic pancreatitis." (PMID 33916984, 2021). "The discovery of additional SPINK1 variants associated with chronic pancreatitis confirmed that loss of function is indeed the mechanism responsible for the increased disease risk." (PMID 33515547, 2021). "A diverse range of loss-of-function variants in the SPINK1 gene (encoding pancreatic secretory trypsin inhibitor) has been identified in patients with chronic pancreatitis (CP)." (PMID 34828289, 2021). "Taken together, the observations indicate that defective trypsin inhibition by SPINK1 variants is an uncommon mechanism in chronic pancreatitis." (PMID 33515547, 2021). "Patients with chronic pancreatitis (CP) due to SPINK1 gene mutation and HP patients have a potentially high risk of pancreatic exocrine insufficiency, diabetes mellitus, and, of particular importance, pancreatic cancer." (PMID 33375361, 2020).
chronic pancreatitis (continued). "Hereditary pancreatitis can be defined as a patient with recurrent acute or chronic pancreatitis who has a first or second degree relative having similar presentation or one who presents with mutated SPINK1, PRSS1, CFTR, and CTRC genes." (PMID 31588422, 2019). "The first dataset comprised 16 deep intronic variants identified in 52 genetically unexplained Chinese chronic pancreatitis patients by sequencing the entire intronic sequence of the SPINK1 gene." (PMID 30755276, 2019). "The clinical significance of SPINK1 intronic variants in chronic pancreatitis has been previously assessed by various approaches including a cell culture-based full-length gene assay." (PMID 30755276, 2019). "Despite this, carrying the SPINK1 mutation increases an individual's risk of developing chronic pancreatitis 12-fold." (PMID 29515728, 2017). "The SPINK1 mutation results in trypsinogen activation which predisposes to chronic pancreatitis predominately when combined with CFTR gene mutations." (PMID 29515728, 2017). "We present an unusual case of a young male who initially presented with renal colic and was incidentally diagnosed with severe chronic pancreatitis on abdominal imaging, with genetic testing confirming a homozygous SPINK1 mutation." (PMID 29515728, 2017). "Patients with heterozygous CFTR mutations who develop chronic pancreatitis often have coexisting SPINK1 mutations which indicates there is an interaction between these genes." (PMID 29515728, 2017). "As we have shown that the pool of undifferentiated spermatogonia is not affected, we can envisage a method of treatment targeting protease activity using a protease inhibitor, as is done for chronic pancreatitis caused by SPINK1 deficiency." (PMID 28554943, 2017). "Mutation in the serine protease inhibitor, Kazal type-1 (SPINK1 gene) increases the chance of an individual developing chronic pancreatitis 12-fold." (PMID 29515728, 2017). "Hereditary chronic pancreatitis associated with a mutation in the serine protease inhibitor, Kazal Type-1 (SPINK-1 gene) is extremely rare." (PMID 29515728, 2017). "SPINK1 (serine protease inhibitor, kazal-type, 1), which encodes human pancreatic secretory trypsin inhibitor, is one of the most extensively studied genes underlying chronic pancreatitis." (PMID 28472998, 2017). "Chronic pancreatitis can be triggered by mutations of SPINK1 that decrease or suppress its trypsin inhibitor function, leading to cell distress." (PMID 28554943, 2017). "SPINK1, a potent protease inhibitor, is also known as pancreatic secretory trypsin inhibitor (PSTI), and mutations in SPINK1 have been associated with chronic pancreatitis." (PMID 26300989, 2015). "The complex interactions between recurrent trypsin-mediated pancreatic injury, alcohol-associated pancreatic injury and SPINK1 polymorphisms in chronic pancreatitis (CP) are undefined." (PMID 18414673, 2008). "Some authors state that compound heterozygous CFTR carriers have a distinct elevated risk for the development of chronic pancreatitis, which is even higher when an additional SPINK1 mutation is present." (PMID 17204147, 2007). "Witt and colleagues described at first an association between mutations of the serine protease inhibitor, Kazal type 1 (SPINK1) and chronic pancreatitis." (PMID 17204147, 2007). "Mutations of SPINK1, the main intraacinar trypsin inhibitor, are associated to idiopathic, alcolholic and the tropical form of chronic pancreatitis." (PMID 17069643, 2006). "Background/Objectives: While complete loss-of-function (LoF) SPINK1 variants in the simple heterozygous state cause chronic pancreatitis, biallelic complete LoF variants result in a rare pediatric disorder termed severe infantile isolated exocrine pancreatic insufficiency (SIIEPI)." (PMID 41009946, 2025).